AFAP1L1 (actin filament associated protein 1 like 1)
Description:
May be involved in podosome and invadosome formation.
Synonyms: FLJ36748
Tractability: PROTAC: ubiquitination databases record sites on it.
Gene: Protein-coding gene on chromosome 5 (149,271,823 to 149,343,637, forward strand). Ensembl gene ENSG00000157510.
Subcellular location: Cytoplasm; Cell projection, podosome; Cell projection, invadopodium; Cytoplasm, cytoskeleton, stress fiber
Gene Ontology:
Molecular function: protein binding
Cellular component: cytoplasm; cytosol; podosome; stress fiber
Genetic constraint (gnomAD): Loss-of-function variants: 77 observed, 98.64 expected, observed/expected ratio (o/e) 0.78, 90% interval 0.65 to 0.94. The upper end of that interval is the gene's LOEUF score, 0.94, which puts it in group 4 of 6, group 1 being the genes least tolerant of losing a copy. Missense variants: 893 observed, 1,009.9 expected, observed/expected ratio (o/e) 0.88, 90% interval 0.84 to 0.94. Synonymous variants: 373 observed, 398.62 expected, observed/expected ratio (o/e) 0.94, 90% interval 0.86 to 1.02.
Homologues: Orthologues: chimpanzee AFAP1L1 (99% identical), macaque AFAP1L1 (97% identical), dog AFAP1L1 (92% identical), rabbit AFAP1L1 (91% identical), guinea pig AFAP1L1 (91% identical), mouse Afap1l1 (89% identical), rat Afap1l1 (88% identical), pig AFAP1L1 (86% identical), tropical clawed frog afap1l1 (64% identical), zebrafish afap1l1a (55% identical), zebrafish afap1l1b (55% identical). Paralogues in human: AFAP1 (46% identical), AFAP1L2 (37% identical).
Diseases named in the same sentence as AFAP1L1 in open-access papers:
AFAP1L1 is named in the same sentence as 17 diseases in open-access papers, as found by Europe PMC text mining. Sharing a sentence is not in itself a finding about the gene and the disease. The quoted sentences say what the papers report.
colorectal cancer (3 papers, 2014 to 2023). A primary or metastatic malignant neoplasm that affects the colon or rectum. "Subsequent studies demonstrated that AFAP1L1 localizes to invadopodia and intersects with several invadopodia pathway components to promote its formation in colorectal cancer and osteosarcoma." (PMID 36631800, 2023). "In this study, we analyzed AFAP1L1 gene expression in tissue samples from colorectal cancer (CRC) patients, and assessed its correlation with other clinicopathologic findings." (PMID 24723436, 2014). "In this study, we found a marked elevation of AFAP1L1 gene expression in colorectal cancer (CRC) tissues as compared to the adjacent normal mucosa." (PMID 24723436, 2014). "Besides, AFAP1L1 also acts as oncogene in colorectal cancer and spindle cell sarcomas." (PMID 36631800, 2023).
osteosarcoma (3 papers, 2014 to 2023). A usually aggressive malignant bone-forming mesenchymal neoplasm, predominantly affecting adolescents and young adults. "For instance, within osteosarcoma cellular lineages, the suppression of AFAP1L1 impeded the formation, cellular adhesion, migration, and infiltration of invasive pseudopods." (PMID 37737201, 2023). "The downregulation of AFAP1L1 in osteosarcoma cells markedly decreased their invasion capability in matrix gels, and the ectopic overexpression of AFAP1L1 in immortalized human mesenchymal stem cells resulted in a significant enhancement of invasiveness." (PMID 24723436, 2014).
gastric cancer (2 papers, 2023). A primary or metastatic malignant neoplasm involving the stomach. "Moreover, they discovered that AFAP1L1 induction facilitated epithelial-mesenchymal transition (EMT) to promote the advancement of gastric cancer by activating CDC42 and ITGA5 signaling pathways, with mediation from VAV2." (PMID 37737201, 2023).
sarcoma (2 papers, 2013 to 2014). A usually aggressive malignant neoplasm of the soft tissue or bone. "We have shown that the induction of AFAP1L1 expression increased cell motility and invasiveness in sarcoma cells." (PMID 23326307, 2013). "Knocking down of the AFAP1L1 gene in sarcoma cells reduced cell invasiveness and forced expression of AFAP1L1 in immortalized human mesenchymal stem cells increased anchorage-independent cell growth as well as cell invasiveness." (PMID 23326307, 2013). "In this study, we explored the transcriptional regulation of AFAP1L1 in order to find factors responsible for the up-regulation of AFAP1L1 expression, which will help us to understand how sarcoma cells gain the malignant phenotype." (PMID 23326307, 2013). "First, we checked AFAP1L1 expression in sarcoma cell lines by RT-PCR and qPCR." (PMID 23326307, 2013). "In addition, it is an intriguing issue whether the AFAP1L1 gene could be a prognostic marker for other malignancies besides sarcomas." (PMID 24723436, 2014). "A recent study revealed that AFAP1L1 interacted with the SH3 domain of cortactin, an F-actin-binding protein Although we had previously reported that AFAP1L1 was associated with the progression of sarcomas, how it functions in the invasiveness of tumor cells remains ill defined." (PMID 23326307, 2013). "In the Western blot analysis, AFAP1L1 was detected in U2OS and MG63 cells but undetectable in SYO-1, Saos2 and HT1080 cells, indicating that the expression of AFAP1L1 was regulated differently among sarcomas at the transcriptional level." (PMID 23326307, 2013). "This phenomenon was also observed in prostate cancer PC-3 cells, indicating that the transcriptional role of Sp3 for the AFAP1L1 gene is not restricted to sarcoma cells." (PMID 23326307, 2013).
spindle cell sarcoma (2 papers, 2013 to 2014). A malignant mesenchymal neoplasm composed of spindle-shaped cells. "We have previously identified actin filament-associated protein 1-like 1 (AFAP1L1) as a metastasis-predicting marker for spindle cell sarcomas by gene expression profiling, and demonstrated that AFAP1L1 is involved in the cell invasion process by in vitro analyses." (PMID 24723436, 2014). "Our previous study identified the AFAP1L1 gene as a prognostic marker for spindle cell sarcomas utilizing a genome-wide cDNA microarray." (PMID 24723436, 2014). "AFAP1L1 was previously identified as a metastasis-predicting marker from the gene-expression profiles of 65 spindle cell sarcomas by our group." (PMID 23326307, 2013).
breast carcinoma (1 paper, 2014). "AFAP1L1 has been reported to be localized to the invadopodia, along with cortactin, in breast cancer cells." (PMID 24723436, 2014).
leukemia (1 paper, 2025). A malignant (clonal) hematologic disorder, involving hematopoietic stem cells and characterized by the presence of primitive or atypical myeloid or lymphoid cells in the bone marrow and the blood. "Besides lymphoma- and/or leukemia-related genes, the most frequently mutated tumor suppressor genes included AFAP1L1, FBN3, MTSS2, and TTLL5, with each being mutated in at least 10% of cHL cases." (PMID 41296384, 2025).
lung carcinoma (1 paper, 2023). "The histogram indicated that AFAP1L1 was significantly expressed in all three types of lung cancer (adeno, large_cell, and squamous), as well as in total lung cancer patients, with the highest expression observed in tip cells." (PMID 37737201, 2023). "To obtain a more comprehensive understanding of the expression of AFAP1L1 in lung cancer endothelial cells, we assessed the expression density of well-known endothelial cell marker genes (PECAM1), tip cell marker genes (DLL4 and CXCR4) and AFAP1L1 in the t-SNE projection." (PMID 37737201, 2023).
lymph node metastasis (1 paper, 2023). "More importantly, GC with lymph node metastasis (LNM) had significantly higher AFAP1L1 expression than those without LNM." (PMID 36631800, 2023). "Besides, GC tissues with lymph node metastasis had significantly higher AFAP1L1 mRNA and protein expression than those without lymph node metastasis, indicating that AFAP1L1 may associate with GC metastasis." (PMID 36631800, 2023).
rectal cancer (1 paper, 2014). A primary or metastatic malignant neoplasm that affects the rectum. "In the multivariate logistic regression analysis for recurrence in patients with rectal cancers, strong AFAP1L1 protein expression was found to be an independent and significant factor." (PMID 24723436, 2014). "Multivariate logistic regression analysis for recurrence in the 80 rectal cancers showed that AFAP1L1 expression was an independent and significant factor, along with the pathological assessment of the regional lymph nodes (pN) status." (PMID 24723436, 2014). "Multivariate analysis revealed that AFAP1L1 was an independent and significant factor for the recurrence of rectal cancers." (PMID 24723436, 2014). "Moreover, the addition of the AFAP1L1 expression level to the lymph node metastasis status provided more predictive information regarding postoperative recurrence in rectal cancers." (PMID 24723436, 2014). "In 80 curative resections for rectal cancers, there was a tendency that the DFS rates were better in those cases immunonegative for AFAP1L1 expression as compared to the strongly immunopositive cases." (PMID 24723436, 2014).
soft tissue sarcoma (1 paper, 2013). A malignant neoplasm arising from muscle tissue, adipose tissue, blood vessels, fibrous tissue, or other supportive tissues excluding the bones. "Considering that Sp3 is expressed at higher levels in soft tissue sarcomas and transactivates the AFAP1L1 gene, targeting Sp3 could be a powerful approach to treating advanced soft tissue sarcomas." (PMID 23326307, 2013).
cancer (5 papers, 2014 to 2023). A tumor composed of atypical neoplastic, often pleomorphic cells that invade other tissues. "Pan-cancer analysis and scRNA-seq data analysis were employed to forecast the association between Actin filament-associated protein 1 like 1 (AFAP1L1) and the development of tumors and endothelial cells." (PMID 37737201, 2023). "Based on the outcomes of differential expression analysis, prognostic evaluation, methylation and phosphorylation analysis, and other correlation analyses, we deduce that AFAP1L1 is intricately linked to the occurrence and advancement of diverse cancer types." (PMID 37737201, 2023). "Similar results were obtained from the TIMER2 database using EPIC, MCPCOUNTER, and XCELL algorithms to examine the association between AFAP1L1 expression and endothelial cells within various cancers." (PMID 37737201, 2023). "Furthermore, we appraised the association between the level of AFAP1L1 expression and survival prognosis of pan-cancer patients by means of the Cox regression analysis using the Gene Set Cancer Analysis (GSCA) database." (PMID 37737201, 2023). "Our pan-cancer investigation of AFAP1L1 revealed a strong association with endothelial cells." (PMID 37737201, 2023). "In addition, we used GSEA to find that AFAP1L1 was associated with multiple biological processes for 33 cancer types in the TCGA database." (PMID 37737201, 2023). "Analysis of associations between AFAP1L1 and 14 functional states in different cancers from the CancerSEA database showed that AFAP1L1 was positively associated with angiogenesis across multiple data sets, what attracts our attention is that it is also positively correlated with hypoxia." (PMID 37737201, 2023). "The mRNA expression of AFAP1L1 gene is up-regulated in the late stage of most human cancer types, including COAD, READ, and STAD." (PMID 37737201, 2023). "We obtained TCGA data for the infiltration of various immune cells from the TIMER database to examine the correlation between AFAP1L1 expression and the levels of tumor-infiltrating immune cells across diverse cancer types." (PMID 37737201, 2023). "Tumor Immune Estimation Resource 2 (TIMER2) database was used to investigate the AFAP1L1 mRNA expression in human cancers." (PMID 37737201, 2023). "Subsequently, we examined the association between DNA methylation and AFAP1L1 expression, and the GSCA results indicated an inverse relationship between them across most cancer types." (PMID 37737201, 2023). "In particular, AFAP1L1 was significantly up-regulated in various cancer types such as CHOL, ESCA, GBM, HNSC, KIRC, LIHC, and STAD, and significantly down-regulated in LUAD, LUSC, BRCA, KIRP, PRAD, and UCES." (PMID 37737201, 2023). "Within this study, we conducted an extensive analysis of numerous multi-omics cancer data sets from various perspectives to further elucidate the functional significance of AFAP1L1 across a spectrum of malignancies." (PMID 37737201, 2023). "Differential mRNA expression of AFAP1L1 between tumor tissues and adjacent normal tissues was compared, revealing that AFAP1L1 was aberrantly expressed in most human cancer types." (PMID 37737201, 2023). "An examination of gene expression profiles across multiple human cancer types by using the Gene Set Cancer Analysis (GSCA) database has demonstrated that the expression level of the AFAP1L1 gene was related to the pathological stage of cancer patients." (PMID 37737201, 2023). "AFAP1L1 was shown to play a role in tumour metastasis and to constitute a cancer prognostic marker, to be localised to invadosomes and along with cortactin, to podosomes." (PMID 25875301, 2015). "Taken together, among the AFAP1 family, AFAP1L1 showed the most cancer-specific upregulated expression pattern in CRC tissues." (PMID 24723436, 2014). "ANKRD37 and AFAP1L1 in the ‘hypoxic group’ have been shown to be involved in migration and invasion of cancer cells." (PMID 25079072, 2014).
cancer (continued). "Given that AFAP1L1 expression is known to be positively correlated with hypoxia signaling in most cancer types, it prompted us to explore whether hypoxia could have an impact on AFAP1L1 expression." (PMID 37737201, 2023). "Interestingly, the results demonstrated that AFAP1L1 expression exhibited a significant and positive correlation with endothelial cells, hematopoietic stem cells, and stroma scores in most cancer types within the TCGA database." (PMID 37737201, 2023). "In this investigation, we ascertained that AFAP1L1 exhibited a linkage with the incidence and progression of numerous tumors and exhibited a significant correlation with the functioning of endothelial cells in the tumor microenvironment via a pan-cancer analysis." (PMID 37737201, 2023). "Besides, signaling pathways associated with cancer progression, such as pathways in cancer, MAPK signaling pathway, were also enriched in KEGG pathway analysis Gene set enrichment analysis (GSEA) using TCGA STAD data showed integrin was the mainly pathway enriched in high AFAP1L1 expression group." (PMID 36631800, 2023).
tumor (5 papers, 2013 to 2023). "Due to the robust expression of AFAP1L1 in endothelial cells within numerous normal tissues, we sought to further investigate whether AFAP1L1 is associated with endothelial cells within the tumor microenvironment." (PMID 37737201, 2023). "Our objective was to scrutinize the function of AFAP1L1 in the pathological formation of new blood vessels and to probe its possibility in the treatment of both neoplasms and neovascular ocular diseases." (PMID 37737201, 2023). "Targeted suppression of AFAP1L1 specifically in endothelial cells in vivo proves effective in inhibiting tumor formation and ocular pathological neovascularization." (PMID 37737201, 2023). "The tumor volumes in the AFAP1L1 knockout group and the normal control group were 767.723 ± 133.645mm3, 738.288 ± 75.122mm3 and 1832.006 ± 106.33 mm3, respectively." (PMID 37737201, 2023). "Subsequently, to determine the impact of AFAP1L1 on tumor angiogenesis, we stained tumor sections with CD31." (PMID 37737201, 2023). "In vivo subcutaneous mouse model further demonstrated that AFAP1L1 downregulation inhibited growth of subcutaneous tumor derived from AGS cells, while AFAP1L1 overexpression obviously promoted tumor growth of MKN74." (PMID 36631800, 2023). "The CPTAC database was used to analyze differences in AFAP1L1 protein phosphorylation levels between normal and primary tumor tissues." (PMID 37737201, 2023). "Our results demonstrated that AFAP1L1 knockdown led to a significant suppression of tumor weight and volume compared to the normal control group." (PMID 37737201, 2023). "To delve deeper into the role of AFAP1L1 in the tumor microenvironment, we generated murine-specific AFAP1L1 shRNA(shAFAP1L1-Mus) to minimize its influence on human A549 tumor cells." (PMID 37737201, 2023). "In conclusion, these data imply that AFAP1L1 knockdown suppresses tumor growth by inhibiting neo-angiogenesis." (PMID 37737201, 2023). "The tumor weight of the AFAP1L1 knockdown group and the normal control group were 0.93525 ± 0.099 g, 0.853 ± 0.106 g and 1.93925 ± 0.095 g, respectively." (PMID 37737201, 2023). "To better comprehend the effect of AFAP1L1 on the tumor microenvironment, we loaded shAFAP1L1-Mus into adeno-associated viruses (AAV) under the control of the endothelial-specific promoter (TIE) (AFAP1L1-ECKD #1-#2) for subsequent in vivo experiments." (PMID 37737201, 2023). "The Tumor Immune Single-cell Hub 2 (TISCH2) database was employed to examine the TCGA survival data for AFAP1L1." (PMID 37737201, 2023). "Overall, the AFAP1L1 gene expression levels were upregulated in the tumor tissues in 69% of the cases (42/61)." (PMID 24723436, 2014). "AFAP1L1-transduced cells showed accelerated tumor growth in vivo, presumably reflecting the anoikis resistance of these AFAP1L1-expressing cells." (PMID 24723436, 2014). "This downregulation of AFAP1L1 expression following siRNA treatment was confirmed by western blotting using extirpated tumor tissues." (PMID 24723436, 2014). "In 19 of 33 cases, the AFAP1L1 gene expression levels were upregulated in the tumor tissues more than twofold higher than in the adjacent normal mucosa (log ratio >1.0)." (PMID 24723436, 2014). "In univariate and multivariate analyses, higher expression of AFAP1L1 was found to contribute to the occurrence of distant metastases, along with patient age and tumor grade." (PMID 23326307, 2013). "In addition, AFAP1L1 promotes GC cells proliferation, migration, invasion in vitro and tumor growth, metastasis in vivo by inducing epithelial-to-mesenchymal transition (EMT)." (PMID 36631800, 2023). "At last, a series of experiments proved our assumption and ML141, a CDC42 GTPase inhibitor, may be useful to prevent tumor progression for GC patients with high AFAP1L1 expression." (PMID 36631800, 2023).
tumor (continued). "Tumor xenograft model and ocular pathological neovascularization model were constructed as well as Isolectin B4 (IsoB4) staining and immunofluorescence staining were used to assess the effects of AFAP1L1 on the progression of neoplasms and neovascular eye diseases in vivo." (PMID 37737201, 2023). "In this study, we confirmed that AFAP1L1 could not only promote GC cells proliferation, migration, invasion in vitro but also tumor growth and metastasis in vivo." (PMID 36631800, 2023). "In the AFAP1L1 siRNA-3 treatment group, the tumor growth was significantly inhibited." (PMID 24723436, 2014). "However, there is a possibility that AFAP1L1 can exert another tumor-promoting effect." (PMID 24723436, 2014). "Furthermore, the local administration of a siRNA against AFAP1L1 significantly suppressed the in vivo tumor growth of xenografts, suggesting that AFAP1L1 might be a candidate therapeutic target for CRCs." (PMID 24723436, 2014).
AFAP1L1 also shares sentences with these, for which no sentence is quoted: colon cancers (1 paper); lymphoma (1); ovarian carcinoma (1); prostate carcinoma (1).